IL6 (interleukin 6)
Diseases named in the same sentence as IL6 in open-access papers (continued):
Sharing a sentence is not in itself a finding about the gene and the disease.
Aqueductal stenosis (1 paper, 2021). Stenosis of the cerebral aqueduct (also known as the mesencephalic duct, aqueductus mesencephali, or aqueduct of Sylvius), which connects the third cerebral ventricle in the diencephalon to the fourth ventricle, which is between the pons and cerebellum. "IL-6 was significantly increased in patients with PHH compared to those with aqueductal stenosis (p = 0.0295), myelomeningocele (p = 0.0002), and TBI (p = 0.0282)." (PMID 33514409, 2021).
ascariasis (1 paper, 2016). An infection that is caused by the roundworm Ascaris lumbricoides, many cases of which remain asymptomatic. "Human ascariasis is characterized by a Th2 and regulatory immune response, although innate production of IL-5, IL-6 and TNF-α seems to play crucial role in the pathogenesis of experimental larval ascariasis." (PMID 26814713, 2016).
ascending aortic aneurysm (1 paper, 2025). "In accordance, either knockdown of Tnfα or Igf1 in CX3CR1+ macrophages reduced vascular inflammation, as evidenced by the downregulation of Mcp1, Il6, and Cxcl2, and subsequently ameliorated both aortic root and ascending aortic aneurysm progression as well as related aortic wall pathologies." (PMID 39817456, 2025).
Astigmatism (1 paper, 2023). A type of refraction error associated with abnormal curvatures on the anterior and/or posterior surface of the cornea. "Negative correlation included K1 with GSH/GSSG ratio, astigmatism axis with TNF-α, and CCT with IL-6." (PMID 36904299, 2023).
ataxia telangiectasia (1 paper, 2015). Ataxia-telangiectasia is the association of severe combined immunodeficiency (affecting mainly the humoral immune response) with progressive cerebellar ataxia. "We found that cigarette smoke accelerates telomere dysfunction via reactive oxygen species in vitro and may be associated with ataxia telangiectasia mutated-dependent secretion of inflammatory cytokines interleukin-6 and -8." (PMID 26386121, 2015).
autoimmune gastritis (1 paper, 2024). Inflammation of the body fundic mucosa of the stomach. "IL-6 dysregulation is also observed in gastrointestinal tract disorders, although the role of IL-6 in autoimmune gastritis remains unclear." (PMID 39193325, 2024).
autoimmune glomerulonephritis (1 paper, 2024). An autoimmune form of glomerulonephritis (disease). "Promotion of autoimmune glomerulonephritis by IL-17 is mediated, in part, by m6A modification of RNA and functional IGF2BP2 (IMP2) binding of selected transcripts: Cebpd, Ccl7, Mt2, Il-6, and Cxcl1." (PMID 39338937, 2024).
Autosomal dominant hyper-IgE syndrome (1 paper, 2021). 2000 IU/ml), recurring staphylococcal skin abscesses, and recurrent pneumonia with formation of pneumatoceles. "Patients with autosomal dominant hyper-IgE syndrome (Job’s syndrome, caused by STAT3 mutation) have defects in IL-6, IL-23 and IL-22 signaling with reduced TH17 cells, and are prone to have mucocutaneous candidiasis, staphylococcus aureus infection, and probably viral infections." (PMID 34539646, 2021).
benign soft tissue tumors (1 paper, 2017). "Serum IL-6 levels (median: 9.04 pg/ml) in patients with STS were statistically higher than those (3.31 pg/ml) in patients with benign soft tissue tumors." (PMID 28851899, 2017). "The IL-6 levels in patients with STS were statistically higher than those in patients with benign soft tissue tumors (odds ratio [OR]: 1.17, p < 0.0001)." (PMID 28851899, 2017). "The aim of the present study was to determine whether serum IL-6 levels could be useful to assume the differentiation of benign soft tissue tumors from STS." (PMID 28851899, 2017). "The aim of the present study was to determine whether serum IL-6 levels could be useful to assume the differentiation of benign soft tissue tumors from STS and to investigate the possible value of IL-6 for survival and oncological events in patients with STS." (PMID 28851899, 2017). "However, there have been no reports concerning the diagnostic value of IL-6 in the differentiation of benign soft tissue tumors and STS." (PMID 28851899, 2017). "An elevated IL-6 level (>6.567 pg/ml) was observed in 37 of 59 patients with STS and 8 of 40 patients with benign soft tissue tumors." (PMID 28851899, 2017). "The median IL-6 level was 9.04 pg/ml (mean: 35.9 pg/ml, range: 0–552.6 pg/ml) in patients with STS and 3.31 pg/ml (range = 0–13.5 pg/ml, mean = 3.89 pg/ml) in patients with benign soft tissue tumors." (PMID 28851899, 2017).
Blau syndrome (1 paper, 2022). Blau syndrome (BS) is a rare systemic inflammatory disease characterized by early onset granulomatous arthritis, uveitis and skin rash. "While several new therapies have been reported, including JAK inhibitors, anti-IL-6 and anti-IL-1 therapies, anti-TNF therapy plays a central role in the treatment of Blau syndrome." (PMID 35711422, 2022).
bleeding (1 paper, 2017). "Serum IL-6 levels were significantly raised in aSAH patients who presented with additional intraventricular or intracerebral bleeding or both simultaneously at several days in comparison to that of patients who had only blood in subarachnoid space." (PMID 29194369, 2017).
blepharitis (1 paper, 2022). Inflammation of the eyelids near the eyelashes. "Studies have reported that levels of chronic inflammatory cytokines such as IL-1β, IL-6, TNF-α and IFN-γ are higher in depressed patients, suggesting a similarity in the mechanism of blepharitis development." (PMID 35372440, 2022).
blood disease (1 paper, 2022). A disease that occurs in the blood. "Recently, much work has been done to explore the association of inflammation, as reflected by C reactive protein (CRP), interleukin-6 (IL-6), and IL-8, with VCZ concentration in transplantation patients, patients with blood diseases, and critically ill patients." (PMID 35462904, 2022).
bone marrow disorder (1 paper, 2025). Any disease of the bone marrow. "Certain strains, such as Lactobacillus and Bifidobacterium, have been shown to lower levels of inflammatory markers such as C-reactive protein (CRP) and interleukin-6 (IL-6), which are typically increased in bone marrow disorders." (PMID 40292219, 2025).
bovine tuberculosis (1 paper, 2024). "The identification of IL-6 as an early marker of bovine tuberculosis in the bovine species." (PMID 38399810, 2024).
breast cyst (1 paper, 2016). A fluid-filled closed cavity or sac that is lined by an EPITHELIUM and found in the BREAST. "Contrarily, the levels of visfatin/NAMPT and TNF-α were significantly increased, and IL-6 levels were similar in the breast cyst fluid and plasma in both study groups." (PMID 27293305, 2016). "In turn, IL-6 levels in breast cyst fluid and plasma were similar in both study groups." (PMID 27293305, 2016). "However, contrary to this study we did not observe association between TNF-α and IL-6 in breast cyst fluids, but in accordance we found a negative association between TNF-α and estradiol levels." (PMID 27293305, 2016). "In addition, we found an inverse relation between IL-6 and estradiol levels in breast cyst fluid." (PMID 27293305, 2016). "Contrary to leptin, resistin, and adiponectin, IL-6 levels were similar and the levels of visfatin/NAMPT and TNF-α in breast cyst fluid were significantly greater than in the circulation in both study subgroups." (PMID 27293305, 2016).
bubonic plague (1 paper, 2012). A plague in which the bacteria have infected the lymphatic system. "A recent study of the systemic phase of bubonic plague due to fully virulent Y. pestis CO92 showed high levels of the PMN maturation factor G-CSF, chemokines CXCL1 and CCL2, as well as cytokines IL-6 and Il-1α in plasma." (PMID 23248776, 2012).
Burkholderia Infections (1 paper, 2017). Infections with bacteria of the genus BURKHOLDERIA. "Since Nramp1 is well-known to have pleiotropic effects on release of pro-inflammatory cytokines, including IL1-β, TNF-α and IL-6, in response to bacterial uptake, we also investigated the effects of Nramp1 on production of pro-inflammatory cytokines in response to Burkholderia infection." (PMID 28848712, 2017).
Calcium oxalate nephrolithiasis (1 paper, 2025). The presence of calcium- and oxalate-containing calculi (stones) in the kidneys. "At the regulatory level of pro-inflammatory cytokines, interleukin-1β (IL-1β) and interleukin-6 (IL-6), as core mediators of inflammatory responses, play pivotal regulatory roles in Calcium Oxalate Nephrolithiasis formation." (PMID 41019076, 2025). "While both IL-6 and IL-1β are canonical pro-inflammatory cytokines, their mechanistic roles in Calcium Oxalate Nephrolithiasis exhibit distinct divergence." (PMID 41019076, 2025). "Bidirectional effects of IL-6 in Calcium Oxalate Nephrolithiasis formation." (PMID 41019076, 2025). "Paradoxically, in ethylene glycol-induced rat models of Calcium Oxalate Nephrolithiasis, elevated IL-6 levels exhibit significant positive correlation with oxidative stress marker 8-OHdG, implicating its role in promoting crystal deposition through ROS-mediated cascades." (PMID 41019076, 2025). "Furthermore, emerging studies suggest that the elevated expression of IL-1β and IL-6 in Calcium Oxalate Nephrolithiasis may also depend on NF-κB and MAPK signaling pathway regulation." (PMID 41019076, 2025).
carbohydrate metabolism disorders (1 paper, 2024). "In diagnosing carbohydrate metabolism disorders, the use of adiponectin, TNF-α, IL-6, resistin, IL-1β and IL-23 in women, and IL-23 in men should be considered." (PMID 39769504, 2024).
catalepsy (1 paper, 2013). A nervous system disorder characterized by diminished responsiveness and consciousness, and rigidity of the body. "Thus, in this study we attempted to investigate the effect of chronic administration of 8-OH-DPAT on 6-OHDA-induced catalepsy and possible involvement of TNF-α, IL-1β and IL-6." (PMID 24570834, 2013). "The role of pro-inflammatory cytokines in the pathogenesis of PD has been shown in several studies, although the effect of chronic administration of 5-HT1A receptor agonists on 6-OHDA-induced catalepsy and the role of cytokines such as TNF-α, IL-1β and IL-6 has not been clearly studied yet." (PMID 24570834, 2013).
cerebral artery occlusion (1 paper, 2022). "OPG has been shown to be upregulated by ischemia in juvenile rats and mice and in a murine model of middle-cerebral artery occlusion, OPG deletion results in decreased infarct volume, reduced brain edema, downregulation of IL-6 and TNF-α, and diminished infiltration of macrophages." (PMID 36403069, 2022).
Cervical lymphadenopathy (1 paper, 2016). Enlarged lymph nodes in the neck. "This is the first case of IgG4-RD cervical lymphadenopathy associated with such a high level of IL-6." (PMID 27142509, 2016).
cherubism (1 paper, 2018). Cherubism is a rare, self-limiting, fibro-osseous, genetic disease of childhood and adolescence characterized by varying degrees of progressive bilateral enlargement of the mandible and/or maxilla, with clinical repercussions in severe cases. "As cherubism was recently described as being an auto-inflammatory bone disease, we focused on the expression of genes involved in osteoclastogenesis (RANK, RANKL, M-CSF, OPG, NFATc1), bone formation (ALP, Osteocalcin), and inflammation (IL6, IL6R, TNFα, TNFR1, TNFR2, IL17)." (PMID 30236129, 2018).
childhood absence epilepsy (1 paper, 2023). A familial generalized pediatric epilepsy, characterized by very frequent (multiple per day) absence seizures, usually occurring in children between the ages of 4 and 10 years, with, in most cases, a good prognosis. "In agreement with that, IL-6 and IL-8 levels in the cerebrospinal fluid fluid have indeed been linked to human childhood absence epilepsy and valproic acid treatment lowers IL-6 serum levels in children with tonic–clonic generalized seizures." (PMID 37583518, 2023).
Chlamydia pneumonia (1 paper, 2021). "Iron chelation is shown to be effective in blunting the in-vitro production of IL-6 following infection with influenza virus and Chlamydia pneumonia." (PMID 34608227, 2021).
choroideremia (1 paper, 2025). Choroideremia (CHM) is an X-linked chorioretinal dystrophy characterized by progressive degeneration of the choroid, retinal pigment epithelium (RPE) and retina. "The elevated level of serum IL-6 observed in Chm-cKO choroideremia mice suggests a potential pathogenic role, which may facilitate the recruitment and migration of immune cells to the retina and surrounding tissues." (PMID 40332248, 2025). "Furthermore, elevated levels of proinflammatory cytokines, including IL-6, were detected in the serum of Chm-cKO choroideremia mice." (PMID 40332248, 2025).
Chronic constipation (1 paper, 2021). Constipation for longer than three months with fewer than 3 bowel movements per week, straining, lumpy or hard stools, and a sensation of anorectal obstruction or incomplete defecation. "We evaluated patients’ incidence of chronic constipation, levels of interleukin-6 (IL-6), T cells and body mass index in two groups." (PMID 33675295, 2021). "CD patients with visceral obesity has higher incidence of chronic constipation (81% vs. 57%, P = 0.028), higher IL-6 levels (15.28 pg/ml vs. 9.429 pg/ml, P = 0.007) and lower CD4+ T cells (32.7% vs. 44.0%, P < 0.001)." (PMID 33675295, 2021). "In conclusion, visceral obesity lead to chronic constipation, higher level of IL-6 and lower immune function for CD patients in the remission period." (PMID 33675295, 2021). "In our study, only CD patients with visceral obesity suffered from chronic constipation, increased IL-6 level, and decreased immune function rather than UC patients." (PMID 33675295, 2021).
chronic granulomatous disease (1 paper, 2015). Chronic granulomatous disease (CGD) is a rare primary immunodeficiency, mainly affecting phagocytes, which is characterized by an increased susceptibility to severe and recurrent bacterial and fungal infections, along with the development of granulomas. "In a model of murine chronic granulomatous disease pioglitazone increased TGFβ and IL-10 while decreasing KC (mouse homologue to IL-8), IL-6, and TNFα expression." (PMID 26713087, 2015).
chronic nasopharyngitis (1 paper, 2025). "In chronic nasopharyngitis, inflammatory cytokines such as tumor necrosis factor alpha (TNF-α), interleukin 6 (IL-6), and IL-1β are persistently elevated in NALT, contributing to systemic fatigue, low-grade fever, and immune hypersensitivity." (PMID 41024755, 2025).
Chronic tubulointerstitial nephritis (1 paper, 2025). Chronic inflammation of the kidney affecting the interstitium of the kidneys surrounding the tubules. "Persistent infection triggers a prolonged inflammatory response, with elevated levels of pro-inflammatory cytokines such as interleukin-6 (IL-6) and tumor necrosis factor-alpha (TNF-α), leading to chronic tubulointerstitial nephritis." (PMID 40400807, 2025).
Chylothorax (1 paper, 2023). The presence of chyle in the thoracic cavity. "Resolution of chylothorax suggests that the influence of IL-6 on the endothelial cell-to cell junction could be managed successfully." (PMID 37832125, 2023). "Given no preexisting chylothorax before CAR-T transfusion, the chyle leakage is speculated to be correlated with high IL-6 release that induced endothelial activation and coagulation activation." (PMID 37832125, 2023).
clostridium difficile infection (1 paper, 2023). Symptomatic infection due to the spore-forming bacterium clostridium difficile. "For example, in Clostridium difficile infection, S100β activates the RAGE/phosphoinositide 3-kinase (PI3K)/NF-κB pathway, causing an increase in IL-6 expression, leading to IEB damage and intestinal inflammation." (PMID 37779161, 2023).
Cluster headache (1 paper, 2025). A type of headache characterized by repeated attacks of unilateral pain lasting 15 to 180 minutes and associated with local autonomic signs. "IL-6 facilitates the acute phase response (raising CRP) and can modulate pain pathways; in fact, an IL-6 blocker (tocilizumab) has shown some benefit in cluster headache, hinting at a role in cranial pain disorders." (PMID 41377228, 2025).
CMV retinitis (1 paper, 2014). "They concluded that inflammatory IRU can be differentiated from active CMV retinitis by the presence of IL-12 and less IL-6 and absence of detectable CMR replication." (PMID 25089078, 2014).
CNS leukemia (1 paper, 2026). "CNS leukemia-associated seizures are primarily driven by blood-brain barrier (BBB) disruption following leukemic infiltration, which triggers a neuroinflammatory cascade involving pro-inflammatory cytokines such as IL-6 and TNF-α, and impairs glutamate homeostasis." (PMID 41977486, 2026).
common variable immunodeficiency (1 paper, 2023). "However, in patients with common variable immunodeficiency (CVID) and dysfunctional B lymphocytes, the disease often takes a severe form, necessitating ICU admission, mechanical ventilation, and treatment with IL-6-blocking drugs." (PMID 38130842, 2023).
compartment syndrome (1 paper, 2025). Elevated pressure in a confined space enclosed by fascia or eschar, which may lead to vascular compromise and subsequent ischemic injury to the tissue within the space. "However, the results of this study form a hypothesis that the complications of fluid creep such as compartment syndrome can directly lead to increases in inflammatory cytokines like IL-6 and IFN-γ in the zone of stasis." (PMID 40843802, 2025).
congenital toxoplasmosis (1 paper, 2015). Toxoplasma infection that is present from birth. "However, a detailed description of IL6 molecular changes, possibly associated with congenital toxoplasmosis development, would be a challenge." (PMID 26385345, 2015). "So far, several studies have shown some contribution of the encoded IL6 and IL1β cytokines to immune responses against T. gondii, although no such research has been performed for congenital toxoplasmosis." (PMID 26385345, 2015). "Considering our outcomes, as presented in this paper, the GC heterozygotic status at the IL6 −174 G>C SNP, as well as the presence of C alleles at both IL6 and IL1B +3954 C>T SNPs, seems to have been involved in the occurrence of congenital toxoplasmosis in the studied fetuses and neonates." (PMID 26385345, 2015). "We also suggest that further studies on the role of IL6 and IL1 SNPs, performed with larger groups of patients with congenital toxoplasmosis, would be beneficial to verify our results." (PMID 26385345, 2015).
convulsion (1 paper, 2014). A rapid and repeated body muscle contract that results in an uncontrolled shaking of the body. "Results from a number of studies have indicated that convulsions caused by viral infections may be associated with IL-6." (PMID 24348794, 2014).
cortical atrophy (1 paper, 2025). "Combined cytokines and chemokines, including CRP and IL-6, have been linked to severe cortical atrophy due to enhanced Aβ influx, reduced clearance across the BBB, and increased neural production of Aβ." (PMID 41294487, 2025).
Cough (1 paper, 2024). A sudden, audible expulsion of air from the lungs through a partially closed glottis, preceded by inhalation. "Decreased levels of IL-6 in cough groups may result from the decreased anti-inflammatory mechanisms, resulting in cough." (PMID 38341543, 2024). "In the present study, we investigated the signalments, comorbidities, fluoroscopic characteristics, and serum biomarkers (MMP-9, IL-6, SP-A, and SDC-1) of 51 dogs with TC with different cough grades." (PMID 38341543, 2024).
cowpox (1 paper, 2013). A mild, eruptive skin disease of milk cows caused by cowpox virus, with lesions occurring principally on the udder and teats. "The role of IL-6 induction in cowpox pathogenesis remains still unclear but a recent article evidenced that IL-6, IL-8 and CXCL1, produced upon in vitro CPXV-BR infection, could be responsible for chemotaxis of monocytes in vitro." (PMID 23457480, 2013).